RN7SL584P (RNA, 7SL, cytoplasmic 584, pseudogene)
Gene: Miscellaneous RNA gene on chromosome 15 (20,095,733 to 20,096,029, reverse strand). Ensembl gene ENSG00000239471.
Homologues: Orthologues: chimpanzee Metazoa_SRP (99% identical), macaque Metazoa_SRP (93% identical). Paralogues in human: RN7SL400P (99% identical), RN7SL633P (97% identical), RN7SL1 (79% identical), RN7SL2 (79% identical), RN7SL3 (79% identical), RN7SL220P (77% identical), RN7SL679P (76% identical), RN7SL464P (76% identical), RN7SL797P (76% identical), RN7SL868P (76% identical), RN7SL127P (76% identical), RN7SL655P (75% identical), and 701 more.